TUG1 (taurine up-regulated 1)
Synonyms: FLJ20618; NCRNA00080; LINC00080; TI-227H
Gene: Protein-coding gene on chromosome 22 (30,969,245 to 30,979,395, forward strand). Ensembl gene ENSG00000253352.
Subcellular location: Nucleus membrane; Mitochondrion membrane; Cytoplasm
Gene Ontology:
Molecular function: cis-regulatory region sequence-specific DNA binding
Cellular component: cytoplasm; mitochondrial membrane; nuclear membrane; nucleus
Homologues: Orthologues: pig TUG1 (98% identical), mouse Tug1 (92% identical), rat Tug1 (92% identical).
Diseases named in the same sentence as TUG1 in open-access papers:
TUG1 is named in the same sentence as 199 diseases in open-access papers, as found by Europe PMC text mining. Sharing a sentence is not in itself a finding about the gene and the disease. The quoted sentences say what the papers report.
osteosarcoma (76 papers, 2014 to 2025). A usually aggressive malignant bone-forming mesenchymal neoplasm, predominantly affecting adolescents and young adults. "In osteosarcoma tissue samples, TUG1 is overexpressed, and its overexpression is linked to a poor prognosis." (PMID 37190068, 2023). "For example, the taurine upregulated gene 1 (TUG1), as a potential oncogene, has been found to be abnormally expressed in osteosarcoma (OS) and has been associated with distant metastasis." (PMID 33109235, 2020). "In blood samples of osteosarcoma patients, TUG1 expression levels were decreased in postoperative patients in comparison with preoperative patients, and the changes of TUG1 expression were significantly associated with disease status." (PMID 28353666, 2017). "In osteosarcoma TUG1 usually is overexpressed causing high cell proliferation and a low apoptosis rate, whereas in other cancer tissues TUG1 is down-regulated." (PMID 25119862, 2014). "In the subgroup analysis by cancer type, elevated TUG1 expression was associated with poorer survival in patients with gastrointestinal cancer, urinary tumors, gynecological tumors, hematological tumors, and osteosarcoma." (PMID 33747256, 2021). "In osteosarcoma cells, TUG1 expression is associated with tumor migration and invasion." (PMID 33059750, 2020). "Taken together, TUG1 may not only serve as a prognostic and therapeutic, but also diagnostic and surveillance-marker in patients with osteosarcoma." (PMID 29657304, 2018). "Besides, other important hallmarks of osteosarcoma demonstrate close association with TUG1." (PMID 33639865, 2021). "The lncRNA TUG1 has been reported to show up-regulated expression in osteosarcoma, and can also inhibit the apoptosis of osteosarcoma cells." (PMID 41226525, 2025). "The potency of osteosarcoma cell replication was diminished, and the apoptosis was enhanced with the suppression of TUG1 with siRNA." (PMID 39015175, 2024). "When samples from osteosarcomas were compared with neighboring normal tissues, the expression of the lncRNA TUG1, which is situated on chromosome 22q12.2 and is 7.1 kb in size, was noted to be amplified." (PMID 39015175, 2024). "When TUG1 is inhibited, the proliferation of cancer cells decreases, and the replication efficiency of osteosarcoma cells decreases." (PMID 39015175, 2024). "Another investigation demonstrated that hsa-miR-425-5p inactivates the Wnt/β-catenin signaling pathway, consequently reducing the expression of MALAT1 and TUG1 in osteosarcoma, thereby inhibiting tumor progression." (PMID 38383747, 2024). "TUG1 was also shown to promote osteosarcoma proliferation, migration, and invasion via miR-219a-5p/PI3K/AKT signaling pathway." (PMID 37620425, 2023). "It is interesting to note that osteosarcoma tissue clinical samples have high levels of TUG1 expression, while osteosarcoma cell line U2OS has impaired TUG1 expression, which slows cell growth and favors cell death." (PMID 37190068, 2023). "Polydatin also exerted therapeutic effects against doxorubicin-resistant osteosarcoma by suppressing TUG1/Akt signaling, promoting apoptosis and suppressing cell proliferation." (PMID 36235012, 2022). "Higher lncRNA TUG1 expression appears to be predictive of distant metastases and advanced tumor stage and could serve as a biomarker for poor prognosis in cancers; lncRNA TUG1 may stimulate the development of osteosarcoma, which can serve as a prognosis and diagnostic marker." (PMID 35132340, 2022). "For instance, lncRNA TUG1 was identified as an oncogene in osteosarcoma and enhanced osteosarcoma cell growth through modulating the expressions of miR‐212‐3p and FOXA1." (PMID 31984680, 2022). "Studies have reported that lncRNA taurine-upregulated gene 1 (TUG1) mediates the progression of osteosarcoma and bladder cancer by stimulating cell proliferation." (PMID 35565245, 2022).
osteosarcoma (continued). "The up-regulation of lncRNA TUG1 expression was significantly correlated with larger tumour size and late stages of lymph node metastasis in patients with osteosarcoma." (PMID 34039257, 2021). "Taurine-up regulated gene 1 (TUG1) plays an important role in the formation, invasion, and metastasis of osteosarcoma." (PMID 34128849, 2021). "In this study, meta-analysis and bioinformatics were adopted to analyze the mechanism of the occurrence and development of osteosarcoma, so as to explore the value of TUG1 in evaluating the prognosis of patients with osteosarcoma." (PMID 34128849, 2021). "The expression of lncRNA TUG1 in osteosarcoma was significantly higher than that in adjacent normal bone tissue." (PMID 34039257, 2021). "Overall, these findings suggest that NEAT1 and TUG1 are attractive targets for osteosarcoma therapy." (PMID 34298879, 2021). "lncRNA TUG1 knockout inhibited glucose consumption, lactic acid production, and reduced the cell viability of osteosarcoma cells." (PMID 34039257, 2021). "Yang and colleagues investigated the oncogenic mechanisms of lncRNA taurine-upregulated gene 1 (TUG1) in osteosarcoma." (PMID 33652661, 2021). "lncRNA TUG1 promoted the development of osteosarcoma through runt-related transcription factor 2 (RUNX2)." (PMID 34039257, 2021). "Polydatin inhibition of Akt signalling, mediated by lncRNA TUG1, suppressed the proliferation of doxorubicin-resistant osteosarcoma and promoted its apoptosis." (PMID 34039257, 2021). "For example, lncRNA TUG1 suppressed miR-132-3p expression via direct interaction, and delivery of miR-132-3p inhibitor partially flattened the effect of lncRNA TUG1 downregulation on the apoptosis of osteosarcoma cells." (PMID 34517787, 2021). "This study will provide evidence-based medical evidence for the relationship between TUG1 and the prognosis of osteosarcoma." (PMID 34128849, 2021). "In this study, meta-analysis and bioinformatics were adopted to further explore the effects of TUG1 on the prognosis of patients with osteosarcoma and its potential molecular mechanism." (PMID 34128849, 2021). "As a result, inhibition of TUG1/Akt pathway is crucial for polydatin in treatment of doxorubicin-resistant osteosarcoma cell lines." (PMID 33805687, 2021). "Osteosarcoma tissue derived from patients with higher clinical stage, larger tumor size and distant metastasis expressed high TUG1." (PMID 33639865, 2021). "Further, analysis toward osteosarcoma clinicopathologic features demonstrated that overexpression of TUG1 and XIST indicated poor clinical parameters of patients." (PMID 33639865, 2021). "They reported inhibited glucose consumption, lactate production and cell viability of osteosarcoma cells upon TUG1 knockdown." (PMID 33652661, 2021). "In this study, the role of TUG1 in prognosis in patients with osteosarcoma was analyzed by conducting meta-analysis and bioinformatics." (PMID 34128849, 2021). "In this study, it was additionally discovered that TGF-β derived from CAFs can increase the expression of TUG1 in osteosarcoma cells, indicating the contribution of TUG1 to CAF-mediated control of osteosarcoma progression." (PMID 34298879, 2021). "HK2 gene knockout weakened the effect of lncRNA TUG1 overexpression on glycolysis in osteosarcoma cells." (PMID 34039257, 2021). "The induction action of TUG1 on the Wnt/β-catenin pathway was also confirmed in other cancers, such as osteosarcoma, ovarian cancer and oral squamous cell carcinoma." (PMID 34030715, 2021). "TUG1 is not only involved in the molecular mechanism of osteosarcoma, but also closely related to the clinicopathological characteristics and prognosis of osteosarcoma." (PMID 34128849, 2021). "For example, lncRNA TUG1 regulates the proliferation and apoptosis of osteosarcoma by sponging miR-212-3p." (PMID 32370736, 2020).
osteosarcoma (continued). "Subsequently, TUG1 was pervasively studied in multiple cancers, such as osteosarcoma, bladder cancer, non-small-cell lung carcinoma, colorectal cancer, and esophageal squamous cell carcinoma." (PMID 32565910, 2020). "For example, lncRNA TUG1 promotes cell proliferation and suppresses apoptosis in osteosarcoma by regulating the miR-212-3p/FOXA1 axis." (PMID 32302291, 2020). "TUG1 knockdown can also inhibit the proliferation, migration, and invasion of osteosarcoma cells and promote cell apoptosis." (PMID 30936265, 2019). "Recent studies have investigated the role of lncRNA TUG1 as a prognostic factor and ceRNA in osteosarcoma." (PMID 31616462, 2019). "The expression of miR-144-3p was reported to be low in osteosarcoma and lncRNA TUG1 targeting miR-144-3p promoted tumorigenesis through upregulating EZH2 expression." (PMID 30540564, 2018). "The lncRNA Taurine upregulated gene 1 (TUG1) is likewise upregulated in human osteosarcoma tissue as compared to adjacent normal tissue." (PMID 29657304, 2018). "TUG1 promotes cancer metastasis in cancers such as breast cancer, bladder cancer, hepatocellular carcinoma and osteosarcoma." (PMID 28108736, 2017). "TUG1 was over-expressed in human osteosarcoma tissue in comparison with matched adjacent normal tissue." (PMID 28353666, 2017). "TUG1 suppression by siRNA significantly reduced cell proliferation in human osteosarcoma cell lines by apoptosis induction." (PMID 28353666, 2017). "LncRNA TUG1 was overexpressed in several kinds of cancer tissues such as esophageal carcinoma, osteosarcoma and hepatocellular carcinoma." (PMID 28376901, 2017). "Downregulation of TUG1 has been reported to inhibit osteosarcoma cell proliferation and promote apoptosis." (PMID 28754963, 2017). "TUG1 was overexpressed in various solid tumor including osteosarcoma, bladder, esophagus, gastric and liver cancer." (PMID 28069000, 2017). "Previous studies indicated that TUG1 was highly expressed in bladder carcinoma, osteosarcoma and esophageal squamous cell carcinoma." (PMID 27421138, 2016). "TUG1 was accumulates in various tumor tissues such as osteosarcoma, esophageal squamous cell carcinoma, multiple myeloma and bladder urothelial carcinomas, and acted as an oncogenic in tumor growth and development as well." (PMID 26078353, 2015). "Beside, TUG1 is required for regulating carcinogenesis in several of tumors, such as osteosarcoma and melanoma." (PMID 26078353, 2015). "TUG-1 for example is underexpressed in non-small cell lung cancer while overexpression can be found in osteosarcoma cells compared to control tissue." (PMID 25119862, 2014). "For instance, lncRNA–miRNA axes such as MEG3/miR-664a and TUG1/miR-144-3p have been mechanistically linked to OS progression; knockdown of the oncogene lncRNA NEAT1 restores the availability of miR-34c and delays the tumor growth in osteosarcoma." (PMID 41331461, 2025). "Moreover, TUG1 knockdown in the osteosarcoma cell lines, U20S and Saos-2, induced by selective siRNA, leads to a declining cell replication and colony generation, heightened programmed cell death, and the arrest of the cell cycle at the G1/S phase." (PMID 39015175, 2024). "Additionally, polydatin inhibited the progression of doxorubicin-resistant osteosarcoma by regulating the taurine-upregulated gene 1 (TUG1)/Akt signaling pathway." (PMID 36235012, 2022). "Therefore, perhaps TUG1 is a potential biomarker for the prognosis of patients suffering from osteosarcoma." (PMID 34128849, 2021). "Collectively, inhibition of TUG1 and subsequent inactivation of Wnt may be a promising strategy in treating osteosarcoma." (PMID 34130697, 2021). "However, low expression levels of lncRNA TUG1 was an independent indicator of poor prognosis in patients with osteosarcoma." (PMID 34039257, 2021). "TUG1 promotes osteosarcoma proliferation and invasion via AKT activation." (PMID 34425750, 2021).
osteosarcoma (continued). "lncRNA TUG1 promoted the proliferation and invasion of osteosarcoma cells through sponging miR-153." (PMID 34039257, 2021). "Sum up, lncRNA TUG1 have been used as a biomarker in esophageal squamous cell carcinoma, viral hepatitis C and viral hepatitis C-associated hepatocellular carcinoma, NBNC-HCC, lung cancer, bladder cancer, ovarian cancer, osteosarcoma and R/R AML." (PMID 34039257, 2021). "According to previous studies, TUG1 was found to be upregulated and oncogenic in a broad spectrum of cancers, including colorectal cancer, bladder cancer, esophageal squamous cell carcinoma, and osteosarcoma." (PMID 33747256, 2021). "lncRNA TUG1 affected proliferation through miR-153 in osteosarcoma." (PMID 34039257, 2021). "High TUG1 expression correlates with poor prognosis and advanced clinicopathological features, verifying the prognostic-predictive capacity of TUG1 in tumors, especially in gastrointestinal cancer, urinary tumors, gynecological tumors, hematological tumors, and osteosarcoma." (PMID 33747256, 2021). "Taurine upregulated gene 1 (TUG1) was also significantly overexpressed in osteosarcoma tissues." (PMID 34130697, 2021). "Research shows it might significantly induce apoptosis and suppress proliferation in doxorubicin-resistant osteosarcoma cell lines via TUG1 mediated inhibition of Akt pathway in a concentration-dependent manner." (PMID 33805687, 2021). "Forkhead Box M1 (FOXM1) up-regulated the expression of lncRNA TUG1 in osteosarcoma cells." (PMID 34039257, 2021). "For example, lncRNA TUG1 was reported to function as a ceRNA of miR-212-3p, and the inhibition of miR-212-3p could reverse the effect of TUG1 knockdown on osteosarcoma cell proliferation and apoptosis." (PMID 33587010, 2021). "For example, lncRNA TUG1 is upregulated in osteosarcoma cells compared with normal osteoblastic cell line, and its knockdown suppresses glucose consumption, lactate production, and cell viability of osteosarcoma cells." (PMID 34251066, 2021). "Moreover, lncRNA TUG1 down-regulation inhibits proliferation of osteosarcoma cells and promotes apoptosis." (PMID 31850493, 2020). "Dysregulation of lncRNA MEG3 could act as a potential predictor of the progression and poor prognosis of osteosarcoma, and overexpression of lncRNAs UCA1 and TUG1 are essential in the poor prognosis of osteosarcoma." (PMID 31850493, 2020). "For instance, lncRNA TUG1 suppress glioma by promotes osteosarcoma." (PMID 32414422, 2020). "And there were 38 endogenous genes (including ARF1, HSP90AB1, and TUBA1B), 53 TFs (including E2F1, NFKB1, and EGR1), and 858 ncRNAs (including MALAT1, miR-590-3p, and TUG1) were considered as key regulators of osteosarcoma through a series of function enrichment analysis and network analysis." (PMID 30936265, 2019). "Interestingly, TUG1 was found at significantly lower levels in serum samples of osteosarcoma-patients following surgery in comparison to serum samples taken preoperatively." (PMID 29657304, 2018). "Moreover, it diminishes expression of POU class 2 homeobox 1 (POU2F1), thus acting in a TUG1/mir-p-5p/POU2F1-axis in osteosarcoma cells (Saos-2 and U2OS cell lines)." (PMID 29657304, 2018). "Moreover, TUG1 expression was successful at distinguishing osteosarcoma patients from healthy individuals." (PMID 28353666, 2017). "Moreover, TUG1 expression was successful in differentiating osteosarcoma patients from healthy individuals." (PMID 28353666, 2017). "LncRNA TUG1 also might be involved in the regulation the expression of miR-335-5p in osteosarcoma cells." (PMID 29245996, 2017). "Recent study has also found that TUG1 can act as a miR-26a-5p sponge and promote the progression of osteosarcoma by up-regulating ZBTB7C, so TUG1 can be used as a diagnostic marker for osteosarcoma, targeting TUG1 may be an effective strategy for the treatment of osteosarcoma." (PMID 39015175, 2024).